FOSL1 (FOS like 1, AP-1 transcription factor subunit)
Diseases named in the same sentence as FOSL1 in open-access papers (continued):
Sharing a sentence is not in itself a finding about the gene and the disease.
glioma (continued). "The positive correlation between increased NF-κB protein expression and glioma grade as well as its positive correlation with FOSL1 expression strongly indicates NF-κB’s potential as a prognostic marker in glioma patients." (PMID 38856747, 2024). "We previously reported that cell viability was significantly decreased when FOSL1 was silenced by siRNA in glioma cell lines as compared to controls." (PMID 37642779, 2023). "We previously demonstrated that FOSL1 is a response gene for TRPM7 and downregulation of FOSL1 can hinder glioma proliferation and invasion." (PMID 37642779, 2023). "In our study, we found that STAT3 regulates downstream gene target, FOSL1, which is closely related to glioma stemness and therefore facilitates gliomagenesis." (PMID 37642779, 2023). "The protein expression of TRPM7 and GSC markers ALDH1 and FOSL1 were then examined by IHC in glioma brain TMA obtained from glioma patients at BioCoreUSA." (PMID 37642779, 2023). "In the current study, we investigated the role of TRPM7/STAT3/FOSL1 axis in promoting glioma stemness and gliomagenesis." (PMID 37642779, 2023). "Our present study discovered a novel signaling pathway of TRPM7/STAT3/FOSL1 axis that leads to glioma aggressiveness through stemness, suggesting novel therapeutic opportunities for the malignant disease." (PMID 37642779, 2023). "We further examined GSC markers ALDH1 and TRPM7 as well as FOSL1 by immunohistochemistry staining (IHC) in brain tissue microarray (TMA) of glioma patients." (PMID 37642779, 2023). "In the current study, we further detected FOSL1 protein expression using glioma patients brain tissues." (PMID 37642779, 2023). "In all, the current data conform with our previous findings which highlight FOSL1’s potential predictive/prognostic role for glioma patients." (PMID 37642779, 2023). "Together, these results showed that FOSL1 is required for the maintenance of stem cell activity in glioma cells." (PMID 37642779, 2023). "In studies using the human glioma cell lines, we found that FOSL1 mRNA and protein accumulate upon upregulation of TRPM7." (PMID 37642779, 2023). "We found that the expression of TRPM7, ALDH1, and FOSL1 protein is associated with grades of malignant glioma, and TRPM7 protein expression correlates to the expression of ALDH1 and FOSL1 in glioma patients." (PMID 37642779, 2023). "In the present study, we determined the effects of FOSL1 on glioma stem cell (GSC) markers CD133 and ALDH1 by flow cytometry, and the maintenance of stem cell activity by extreme limiting dilution assays (ELDA)." (PMID 37642779, 2023). "We revealed that FOSL1 knockdown reduces the expression of GSC markers CD133 and ALDH1, and FOSL1 is required to maintain stem cell activity in glioma cells." (PMID 37642779, 2023). "These interactions prompted us to investigate the mechanism by which TRPM7 modulates FOSL1 transcriptional activation in glioma cell." (PMID 37642779, 2023). "The study identified eight co-downregulated miRNAs, three co-upregulated miRNAs, and seven genes associated with overall glioma survival, namely, KRAS, IFNB1, ALCAM, ERBB2, STAT3, FOSL1, and EN2." (PMID 36061185, 2022). "These lines of evidence indicate that FOSL1 and EN2, which are involved in our risk assessment model, have prognostic value in various tumors, including glioma." (PMID 36061185, 2022). "In line to what was observed in mouse glioma-initiating cells, FOSL1 silencing in MES BTSC 380 resulted in reduced cell growth with a significant reduction of the percentage of BrdU positive cells compared to Dox-untreated cells." (PMID 34399888, 2021). "Transcription factor FOSL1 is overexpressed in cancer and associated with worse outcomes and EMT as well as with glioma malignancy." (PMID 35008787, 2021). "Fosl1 knock-out (KO) impairs cell growth and stemness in vitro and increases survival in a orthotopic glioma model." (PMID 34399888, 2021).
glioma (continued). "Most importantly, FOSL1 silencing in these non-MES lines had no impact on cell growth, underscoring a mesenchymal context-dependent role for FOSL1 in glioma cells." (PMID 34399888, 2021). "Taken together these findings thrust FOSL1 into the spotlights as the most promising candidate among switch genes as novel therapeutic target for treating human glioma." (PMID 30497369, 2018). "Oncogenic EGFRvIII in glioblastoma cells induces FOSL1, and it modulates the malignant features of glioma cells, so it was suggested as target for therapeutic interventions against malignant gliomas." (PMID 20663135, 2010). "Moreover, the expression levels of FOSL1 gene was elevated in mesenchymal subtypes across four cohorts including The Cancer Genome Atlas (TCGA), Chinese Glioma Genome Atlas (CGGA), CHA, and PRJNA1051047." (PMID 41556041, 2026). "Given that PRMT1 promotes radiotherapy resistance in glioma and was identified as a potential FOSL1 interactor, we hypothesized that FOSL1 interacts with PRMT1." (PMID 41423530, 2025). "NF-κB is an essential transcription factor that activates the FOSL1 promoter in glioma cells." (PMID 40869207, 2025). "The interplay between NF-κB and FOSL1 plays a crucial role in glioma tumorigenesis and stemness." (PMID 38856747, 2024). "NF-κB is a crucial transcription factor activating the FOSL1 promoter in glioma cells." (PMID 38856747, 2024). "To further assess the expression of FOSL1 in glioma and the association between FOSL1 expression and prognosis in glioma patients, we examined the expression of POSTN in normal brain and glioma tissues and analyzed data from the TCGA, CGGA and Rembrandt databases." (PMID 39227950, 2024). "To discern whether the effects induced by FOSL1 are direct or indirect effects, we transfected glioma cells with FOSL1 along with siRNA targeting NF-κB p65 (siNF-κB p65 or siP65) and corresponding controls." (PMID 38856747, 2024). "FOSL1 functions as an AP-1 transcription factor involved in glioma pathogenesis." (PMID 38856747, 2024). "We have reported that FOSL1 promotes glioma proliferation, invasion and enhances glioma stemness." (PMID 38856747, 2024). "Hence, FOSL1 emerges as a key transcription factor contributing to various aspects of tumor development and progression in glioma and other tumor types." (PMID 38791400, 2024). "We have determined the FOSL1 protein’s expression in glioma cells." (PMID 38856747, 2024). "Considering that glioma heterogeneity, attributable in part to the presence of GSCs activity, is an important aspect that contributes to glioblastoma aggressiveness, we examined the effects of FOSL1 on glioma cell stemness by measuring stem cell frequencies." (PMID 37642779, 2023). "In our study, we are the first to report that in glioma, the FOSL1 induction occurred at the transcriptional level in a manner dependent on STAT3, during which phosphorylated post-translational modification was required for STAT3 activation to directly bind to the FOSL1 promoter (ChIP)." (PMID 37642779, 2023). "We found FOSL1 levels were positively correlated with the glioma grades in a total of 75 glioma patients and correlated to the established GSC markers ALDH1 and TRPM7, suggesting FOSL1 is a diagnostic marker and potential therapeutic target for glioma patients." (PMID 37642779, 2023). "In addition, we demonstrated that FOSL1 is a response gene for TRPM7, and the FOSL1 gene serves as an oncogene to promote glioma proliferation and invasion." (PMID 37642779, 2023). "We then investigate whether STAT3 present in nuclear lysate of glioma cells could bind to the − 328 to − 336 and − 378 to − 386 at the FOSL1 promoter by performing ChIP-qPCR." (PMID 37642779, 2023). "In summary, miR-33a with differential expression in glioma and sarcopenia may affect the prognosis of glioma by targeting and regulating FOSL1 and EN2." (PMID 36061185, 2022). "(C) FOSL1 mRNA expression in IDH-wt gliomas, stratified according to NF1 alterations." (PMID 34399888, 2021).
glioma (continued). "We then analyzed the CGGA and TCGA pan-glioma datasets and observed that FOSL1 expression is elevated in the IDH-wt glioma molecular subgroup with a significant upregulation in the MES subtype in bulk tumors, and it is also enriched in MES-like cells at the single-cell level." (PMID 34399888, 2021). "In GBM, it has been shown that FOSL1 modulates in vitro glioma cell malignancy." (PMID 34399888, 2021). "FOSL1 is a bona fide regulator of the glioma-intrinsic mesenchymal (MES) transcriptional signature." (PMID 34399888, 2021). "Furthermore, we show that FOSL1 is a crucial player in glioma pathogenesis, particularly in a MAPK-driven MES GBM context." (PMID 34399888, 2021). "Furthermore, we investigate whether NF-κB p65 present in the nuclear lysate of glioma cells could bind to the FOSL1 promoter by performing ChIP-qPCR." (PMID 38856747, 2024). "In addition, we previously reported that TRPM7 enhances GSC stemness by regulating the established GSC marker ALDH1 and promotes the induction of ALDH1 activity in glioma cells; therefore, we further tested the relationship between FOSL1 and GSC stemness markers TRPM7 and ALDH1 by IHC assay." (PMID 37642779, 2023). "Importantly, high expression levels were associated with worse prognosis in IDH-wt tumors, thus suggesting that FOSL1 could represent not only a key regulator of the glioma-intrinsic MES signature, but also a putative key player in MES glioma pathogenesis." (PMID 34399888, 2021). "FOSL1 over-expression induced differentiation, inhibited proliferation, growth and reduced tumorogenicity of C6 glioma cell line, so it may be a potential target for glioma treatment." (PMID 25182732, 2014). "The up-regulation of FOSL1 ectopic expression and induction of the EMT program in glioma cells can be attributed to the activation of Wnt/β-catenin signaling." (PMID 38791400, 2024). "Subsequent qPCR validation confirmed a significant increase in mRNA levels of CD30, PRKCQ, and ADAM8 in glioma cell lines (A172, U87MG, and PDX-L14) overexpressing FOSL1, which are key regulators at the apex of the NF-κB signaling pathway." (PMID 38856747, 2024). "Firstly, we transfected FOSL1 tagged with GFP and the same vector tagged with Myc-DDK into glioma cells A172, U87MG, and PDX-L14." (PMID 38856747, 2024). "To further verify the biological function of NF-κB in activating FOSL1, we conducted transient transfection of siRNA NF-κB p65 (siNF-κB p65 or siP65) in A172, U87MG, and PDX-L14 glioma cells, along with corresponding controls." (PMID 38856747, 2024). "Specifically, our previous research highlighted how STAT3 triggers FOSL1 transcription by binding to the two GAS elements within the FOSL1 promoter, thereby enhancing glioma stemness." (PMID 38856747, 2024). "In the current study, we found a new pathway that TRPM7 transactivates the FOSL1 gene through transcription factor STAT3 and enhances glioma stemness." (PMID 37642779, 2023). "Based on our previous findings that TRPM7 enhances glioma stemness by triggering STAT3 activation, in the present study, we will investigate the mechanisms by which TRPM7/STAT3/FOSL1 regulatory axis drives stemness and growth in glioma." (PMID 37642779, 2023). "The glioma A172 and PDX-L14 cells were cotransfected with wild-type and mutant FOSL1 constructs at Lys116, together with FOSL1-luc and pRL-TK as an internal control reporter." (PMID 37642779, 2023). "These combined results demonstrated that TRPM7 induced FOSL1 transcriptional activation, which is mediated by the action of STAT3, a mechanism shown to be important in glioma stemness." (PMID 37642779, 2023).
glioma (continued). "FOSL1 and EN2, which are target mRNAs of hsa-miR-33a, can be used to predict the prognosis of glioma based on the results of the bioinformatics analysis." (PMID 36061185, 2022). "(F) Kaplan–Meier survival curves of IDH-wt gliomas in the CGGA and TCGA datasets stratified based on FOSL1 expression." (PMID 34399888, 2021). "Altogether, our data support that FOSL1/FRA-1 regulates MES gene expression and aggressiveness in human gliomas via direct transcriptional regulation, downstream of the NF1-MAPK-FOSL1 signaling." (PMID 34399888, 2021). "Nine TAPPs from the glioma cells (Aim2, Art-4, EphA2, EZH2, Fosl1, PTH-rP, Sox11, Whsc2 and YKL-40) consistently exhibited increased mRNA presence (≥1.9-fold expression) after culturing the cells in hypoxia (1% O2)." (PMID 22957023, 2012). "Hypoxic glioma cell lines increased their mRNA expression for nine TAPP (Aim2, Art-4, EphA2, EZH2, Fosl1, PTH-rP, Sox 11, Whsc2 and YKL-40), as assessed by quantitative reverse transcriptase real-time/polymerase chain reaction (qRT-PCR)." (PMID 22957023, 2012). "FOSL1 and JUN are the downstream factors in the PI3K/Akt pathway, and they can form a stable heterodimer known as AP-1, a transcriptional activator that can influence glioma behavior, reflected by elevated levels of phenotype markers BCL2 and PCNA." (PMID 39554845, 2024). "The Wnt/β-catenin signaling activated the FOSL1 transcription and drove EMT of glioma cells." (PMID 37642779, 2023). "Since FOSL1 is essential for maintenance GSC activity, we hypothesized that it would regulate GSC marker expression levels in glioma cells." (PMID 37642779, 2023). "In this study, hsa-miR-33a was found to regulate FOSL1 and EN2 and affect the prognosis of gliomas." (PMID 36061185, 2022). "Therefore, the multifactorial Cox model developed by FOSL1 and EN2 can better predict glioma prognoses." (PMID 36061185, 2022). "With a multi-factor Cox regression model incorporating FOSL1 and EN2, we obtained ROC curves of 0.702 and 0.709, respectively, suggesting that glioma prognosis can be predicted by FOSL1 and EN2, which are differentially expressed in both cancer and aged muscle." (PMID 36061185, 2022). "To investigate whether FOSL1 and EN2 are independent prognostic factors, we divided all TCGA-glioma samples into high- and low-expression groups based on median gene expression values." (PMID 36061185, 2022). "As FOSL1 is a key glioma regulator, it is expected that other TRPM7-mediated FOSL1 activations could contribute to glioma pathogenesis, other than HOTAIR and miR-301a-3p." (PMID 36844925, 2022). "Moreover, hsa-mir-33a co-targeting FOSL1 and EN2 has a good predictive value for glioma and skeletal muscle reduction." (PMID 36061185, 2022). "(D) Correlation of FOSL1 and NF1 mRNA expression in IDH-wt gliomas." (PMID 34399888, 2021). "This suggests that among the TFs previously characterized (such as FOSL2, STAT3, BHLHB2, and RUNX1), FOSL1 and CEBPB might play a dominant role in the NF1-mediated MES transition that occurs in a glioma cell-intrinsic manner." (PMID 34399888, 2021). "Many of the TAPP were not differentially expressed in the hypoxic cells but nine TAPPs from the glioma cells (Aim2, Art-4, EphA2, EZH2, Fosl1, PTH-rP, Sox11, Whsc2 and YKL-40) consistently exhibited increased mRNA presence after culturing the cells in response to hypoxia." (PMID 22957023, 2012).
glioma (continued). "FOSL1 mRNA expression levels in GBM patients were significantly higher than those in normal individuals as detected by Affymetrix HT HG U133A; furthermore, classical, mesenchymal, and neural molecular subtypes in glioma tissue were higher than those in the normal brain (p < 0.05)." (PMID 38791400, 2024). "Therefore, the functional analyses employing flow cytometry suggest that FOSL1 serves as an oncotarget in GBM, stimulating the growth and proliferation of glioma cells possibly by inhibiting cell apoptosis and promoting their cell entry into the S and G2/M phases of the cell cycle." (PMID 38856747, 2024). "To accomplish the aims of this goal, we cultured glioma cells U87MG and PDX-L14 as gliospheres in a serum-free medium that enriches GSCs, and then silenced FOSL1 expression using lentiviral delivery of shRNA FOSL1, followed by extreme limiting dilution assays (ELDA)." (PMID 37642779, 2023). "To further gain insight into the mechanism by which TRPM7 activates transcription of the FOSL1 gene to contribute to glioma stemness, we constructed a FOSL1 promoter and its GAS mutants followed by luciferase reporter assays and ChIP-qPCR in a glioma cell line and glioma patient-derived xenoline." (PMID 37642779, 2023). "FOSL1 and EN2 may affect the prognosis of gliomas independently." (PMID 36061185, 2022). "Our data indicated that the Wnt pathway activation related genes such as CCN4, FOSL1, LGR6, MMP7, RAC2, SERPINF1 and TCF7 were upregulated, while Wnt pathway inactivation related gene such as CXXC4 was downregulated in radiotherapy treated glioma patients from TCGA database." (PMID 34852024, 2021). "Notably, we observed an abundance of Aif1, Met, and Fosl1 expressing cells not exclusively in hypoxic regions but also in the perivascular space of Pdgfbret/ret glioma sections, indicating a putative opportunistic occupation and exploitation of this glioma niche vacated by pericytes." (PMID 41339360, 2025). "Consistent with the negative correlation of FOSL1 and NF1 mRNA levels in IDH-wt gliomas, NF1-GRD overexpression in two independent MES GBM lines (BTSC 233 and BTSC 232) was associated with a significative downregulation of FOSL1 and FOSL1-regulated genes." (PMID 34399888, 2021). "Importantly, we detected higher level of FOSL1 mRNA in the cohort of IDH-wt gliomas with NF1 alterations (Student’s t test p=0.018), as well as a significant negative correlation between FOSL1 and NF1 mRNA levels (Pearson R = −0.44, p=7.8e-12)." (PMID 34399888, 2021).